MMP8 (matrix metallopeptidase 8)
Diseases named in the same sentence as MMP8 in open-access papers (continued):
Sharing a sentence is not in itself a finding about the gene and the disease.
periodontal disease (135 papers, 2008 to 2026). "IL-1β and MMP-8 serve as complementary salivary biomarkers for periodontal disease, with IL-1β associated with early inflammation and MMP-8 linked to advanced tissue destruction." (PMID 40283051, 2025). "The comparison of these results emphasizes the varying diagnostic usefulness of IL-1β and MMP-8 across different stages of periodontal disease." (PMID 40283051, 2025). "The logistic regression analysis revealed that MMP-8 has a highly significant association (p < 0.01) with the likelihood of periodontal disease, particularly in advanced stages, as indicated by its higher coefficient (0.85)." (PMID 40283051, 2025). "Given that elevated MMP-8 levels are associated with periodontal disease progression, its reduction suggests a potential protective effect of Pycnogenol® on periodontal tissues." (PMID 40362854, 2025). "Studies since 2005 have demonstrated the association between MMP-8 and various periodontal diseases, highlighting its predictive capability." (PMID 39554809, 2024). "Previous studies have shown that the concentration of MMP-8 is associated with the severity of tissue destruction, suggesting its potential as a biomarker for periodontal disease." (PMID 39594474, 2024). "In particular, MMP-8 has been reported to have elevated expression levels in patients with periodontal disease and has also been found to be associated with pocket depth." (PMID 39594474, 2024). "Elevated levels of MMP-8 in GCF have been consistently associated with periodontal disease activity and progression." (PMID 39275315, 2024). "Numerous studies have focused on MMP-8 as a diagnostic biomarker for periodontal diseases, and it has been found in oral fluids, such as mouth rinse, saliva, gingival crevicular fluid (GCF), and peri-implantitis sulcular fluid (PISF)." (PMID 36900047, 2023). "Matrix metalloproteinase (MMP)-8 is an enzyme released primarily from neutrophils that has been extensively investigated as a biomarker and has been implicated in periodontal disease staging and grading." (PMID 36294882, 2022). "According to some systematic reviews, our studied salivary molecules, IL-1β, IL-6, and MMP-8 are recognized as key salivary biomarkers with acceptable diagnostic reliability for periodontal disease." (PMID 35368315, 2022). "The aim of this study was to validate an active matrix metalloproteinase (MMP‐8) point‐of‐care diagnostic tool in COVID‐19 patients with periodontal disease." (PMID 35818743, 2022). "Matrix metalloproteinase‐8 (MMP‐8) is considered as one of the most promising diagnostic markers for periodontal disease." (PMID 35769040, 2022). "Increased expression, release, and activation of uncontrolled MMP-8, along with other MMPs and proteinases, are thought to induce the inflammation associated with tissue destruction in periodontal disease and also other inflammatory diseases." (PMID 35163727, 2022). "A recent systematic review evaluated macrophage inflammatory protein-1α (MIP-1α), IL-1β, IL-6 and MMP-8 as diagnostically acceptable biomarkers for periodontal disease, and the combination of IL-6 and MMP-8 showed the best diagnostic performance." (PMID 35562715, 2022). "Several authors have shown that metalloproteinase-8 (MMP-8), an enzyme responsible for tissue destruction, was positively associated with periodontal disease." (PMID 33498206, 2021). "There is evidence supporting an association between the salivary levels of MMP-8 and periodontal disease clinical parameters." (PMID 35919679, 2021). "MMP-8 is associated with the diagnosis of periodontal disease, the severity of periodontal inflammation, evolution, and follow-up of therapy." (PMID 33567492, 2021). "The diagnostic accuracy for periodontal disease and its severity was significantly enhanced by measuring multiple salivary biomarkers, including MMP8, MMP9, and osteoprotegerin, together with qPCR, for P. gingivalis and T. denticola in dental biofilms." (PMID 33081038, 2020).
periodontal disease (continued). "Conversely, a diagnostic chairside assay for periodontal disease is currently available, which detects the level of matrix metalloproteinase 8 (MMP-8) in the gingival crevicular fluid (GCF) sampled from the gingival sulcus." (PMID 30131827, 2018). "The use of diagnostic strips has been successfully applied to determine the risk of periodontal disease in adolescents based on the levels of the human matrix metalloproteinase MMP-8." (PMID 28654016, 2017). "Recently, several studies have investigated MMP-8 −799 C/T, −381 A/G, and +17 C/G variants in different periodontal diseases." (PMID 27194818, 2016). "The findings of this study suggest that salivary IL-1β and MMP-8 could be effectively integrated into chairside diagnostic tools for the early detection and staging of periodontal disease." (PMID 40283051, 2025). "For example, a recent study demonstrated that elevated levels of IL-1β, IL-6, and MMP-8 are associated with increased periodontal disease severity among diabetic patients, suggesting a bidirectional relationship between glycemic control and periodontal inflammation." (PMID 40283677, 2025). "Elevated levels of MMP-8 and IL-1β in saliva are linked to periodontal disease progression." (PMID 39958008, 2025). "Moreover, auraptene inhibited the Porphyromonas gingivalis bacterial infection which causes periodontal diseases by reducing the secretion and activity of MMP-8 and MMP-9." (PMID 37447286, 2023). "However, not all studies were successful in associating these levels of MMP-8 with smoking and the risk of periodontal disease." (PMID 35163727, 2022). "Periodontal biomarkers, such as MMP-8 and Lactoferrin, that are easy to access and can be rapidly and non-invasively sampled, would be of a predictive nature and a great benefit to patients at risk for early developing periodontal disease." (PMID 34353321, 2021). "High oral fluid MMP-8 levels have been linked to periodontal disease." (PMID 33916950, 2021). "Among all MMPs, MMP-8 and -9 are associated with periodontal disease according to previous studies." (PMID 28117682, 2017). "Furthermore, increased salivary levels of inflammatory protein biomarkers such as interleukin-1β (IL-1β), IL-6 and matrix metalloproteinase-8 (MMP-8) have been described to be associated with periodontal disease status." (PMID 27672500, 2016). "Thus, our results concerning the measurement of the MMP-8 levels in gingival crevicular fluid give information about a possible risk of the progression of periodontal disease." (PMID 21219642, 2011). "By assessing IL-1β and MMP-8 levels in conjunction with clinical parameters, this study highlights the dynamic interplay between inflammatory and destructive processes in periodontal disease." (PMID 40283051, 2025). "The complementary roles of IL-1β and MMP-8 suggest that their combined analysis can enhance the accuracy of periodontal disease diagnostics and staging." (PMID 40283051, 2025). "This study investigates and compares the utility of two salivary biomarkers, interleukin-1 beta (IL-1β) and matrix metalloproteinase-8 (MMP-8), in the early detection and staging of periodontal disease." (PMID 40283051, 2025). "The choice to investigate IL-1β and MMP-8 in this study was based on their complementary roles in the pathogenesis of periodontal disease." (PMID 40283051, 2025). "Studies have shown that higher MMP-8 concentrations correlate with increased pocket depth and tissue destruction, making it a valuable biomarker for periodontal disease activity." (PMID 40283677, 2025). "MMP-8 was chosen for the assay because it is one of the best-described biomarkers of periodontal disease, and, since 2005, there has been a growing body of evidence supporting the diagnostic value of MMP-8." (PMID 41440646, 2025). "The combined application of IL-1β and MMP-8 represents a significant step forward in diagnosing and managing periodontal disease." (PMID 40283051, 2025).
periodontal disease (continued). "Several other salivary diagnostic markers—such as interleukin-1β (IL-1β), matrix metalloproteinase-8 (MMP-8), and bacterial DNA—have also been studied in relation to periodontal disease." (PMID 40725658, 2025). "For example, a study demonstrated that biomarkers such as MMP-8 and interleukin-1β (IL-1β) are significantly elevated in saliva in patients with periodontal disease compared to healthy individuals." (PMID 39958008, 2025). "The correlations between salivary biomarkers and clinical parameters reveal the distinct but complementary roles of IL-1β and MMP-8 in periodontal disease progression." (PMID 40283051, 2025). "In this work, we present a rationally designed electrochemical biosensor for matrix metal-loproteinase-8 (MMP-8), a key salivary biomarker of periodontal disease." (PMID 41149323, 2025). "IL-1β and MMP-8 help fill this gap by providing complementary insights into the progression of periodontal disease." (PMID 40283051, 2025). "The role of IL-1β in periodontal disease activity highlights the inflammatory stage, while MMP-8 represents tissue breakdown." (PMID 40283051, 2025). "Active-matrix metalloproteinase-8 (aMMP-8) has emerged as a key biomarker for periodontal disease diagnosis due to its enzymatic activity being directly linked to tissue destruction, in contrast to total MMP-8 (tMMP-8), which includes inactive forms." (PMID 41300956, 2025). "This study highlights the potential role of salivary biomarkers, including IL-1β and MMP-8, in assessing the severity of periodontal disease." (PMID 40283051, 2025). "The study aimed to analyze MMP-8 levels in periodontal sites of postpartum women and women without a history of pregnancy, comparing health parameters and periodontal disease." (PMID 38928985, 2024). "The determination of MMP-8 concentrations can be useful not only in the detection of periodontal disease, but also in the evaluation of some clinical parameters of this condition and in assessing the effectiveness of periodontal treatments." (PMID 38473967, 2024). "The appearance of specific forms of periodontal disease has been confirmed by an increase in the saliva concentration of matrix metalloproteinase-8 (MMP8), a marker commonly used in humans in the diagnosis of these pathologies." (PMID 38535833, 2024). "Immunoexpression of MMP-8 in CP-gingivae increased according to the increase in periodontal disease severity (stages and grades)." (PMID 38786309, 2024). "MMP-8 and MMP-9 have been linked to periodontal disease in humans, according to a number of studies." (PMID 38535279, 2024). "This indicates that chronic generalized periodontitis is strongly associated with the activity level of salivary MMP‐8, and elevated levels of MMP‐8 in diabetic patients demonstrate the impact of diabetes on periodontal disease." (PMID 38433295, 2024). "The accurate identification of MMP-8 enzyme is crucial for assessing periodontal disease progression." (PMID 39554809, 2024). "Both MMP-8 and MMP-9 levels in GCF have shown promise as diagnostic and prognostic markers for periodontal disease." (PMID 39275315, 2024). "According to our research, higher levels of tartar and inflammation are closely related with elevated MMP-8 levels in saliva, which are indications of periodontal disease and inflammation." (PMID 38535833, 2024). "The levels of salivary MMP‐8 in patients with periodontal disease and diabetes are significantly higher than those in the other two groups." (PMID 38433295, 2024). "The baseline salivary MMP-8 and IL-1β levels of the periodontal disease groups were greater than those of the healthy subjects." (PMID 38086426, 2024). "One notable example is the use of salivary cortisol levels as an indicator of stress, while MMP-8 and -9 show promise as markers for caries and periodontal disease." (PMID 38254696, 2024). "MMP-8 and NE are the only enzymes studied for their predictive value in periodontal disease progression and treatment outcomes." (PMID 39554809, 2024).
periodontal disease (continued). "The appearance of specific forms of periodontal disease has been confirmed by an increase in the saliva concentration of MMP8, a marker commonly used in the diagnosis of these pathologies in humans." (PMID 38535833, 2024). "MMP-8 concentrations in periodontal disease are higher than in healthy patients, suggesting that this proteinase is responsible for the cleavage of collagen fibres in the gingiva." (PMID 36840029, 2023). "Previous investigations have shown that concentration of MMP-8 in oral fluid correlates with the degree of inflammation in a patient with periodontal disease and with dental decay." (PMID 37308912, 2023). "Recent studies have focused on the use of aMMP-8 as a biomarker for periodontal diseases; aMMP-8 refers to the active form of MMP-8, which is produced by neutrophils and other inflammatory cells in response to bacterial infection." (PMID 36900047, 2023). "As periodontal disease progresses, leading to deeper pockets, MMP-8 levels tend to rise, reflecting ongoing periodontal tissue degradation." (PMID 38192959, 2023). "Studies have shown that MMP-8 abundance is closely related to the severity of periodontal disease, and Lactobacillus reduces MMP-8 in gingival crevicular fluid." (PMID 38098816, 2023). "The experimentally-induced periodontal disease was confirmed clinically, histologically and through the determination of salivary MMP-8 concentrations." (PMID 36839899, 2023). "The results of the present study confirm that MF suppresses MMP-1, MMP-2, MMP-8 and IL-8 in LPS-stimulated HGFs suggesting an anti-inflammatory effect of MF and potential adjunct therapeutic role in the treatment of periodontal diseases." (PMID 37189090, 2023). "A major persistent influx of neutrophils, the main cellular source of MMP-8, is characteristic of periodontal diseases." (PMID 37189090, 2023). "Studies have repeatedly shown that MMP-8 is the most concentrated collagenase found in saliva, mouthrinse and gingival crevicular fluid especially in patients with periodontal disease." (PMID 37092545, 2023). "Effective periodontal treatment and MMP inhibitory adjuvant drugs have been shown to have an inhibitory effect in the progression of periodontal disease by reducing the level of MMP-8 in GCF and saliva." (PMID 35163727, 2022). "Doxycycline hyclate is a low-dose tetracycline analog lacking antimicrobial activity, and it is indicated for the treatment of periodontal disease, acting by inhibiting the mechanisms of the MMP-8 and MMP-13 protease." (PMID 35163727, 2022). "Our analysis of the effects of probiotic supplementation on immunological outcomes indicated that the GCF levels of MMP-8 and IL-6 were reduced after probiotic supplementation in patients with periodontal disease." (PMID 35268009, 2022). "The finding of this study further verifies the effect of ADT on periodontal diseases and strengthens the relationship between clinical periodontal parameters and the salivary MMP‐8 level." (PMID 35769040, 2022). "The baseline salivary MMP-8 concentration was also higher in patients with periodontal disease than in healthy participants (p = 0.041)." (PMID 35562715, 2022). "MMP-8 is the main collagenase involved in periodontal disease, with the highest collagenolytic activity in GCF." (PMID 35268009, 2022). "The authors identified that MMP-8, MMP-9, OPG, and IL-1β demonstrated a strong association with periodontal disease progression." (PMID 35626325, 2022). "Given that numerous studies have shown an increased expression of MMP-9 and MMP-8 activity in patients with periodontal disease, they have been proposed as valid indicators of the disease." (PMID 35163727, 2022). "MMP-8 is currently considered one of the most promising biomarkers used for the anticipation, diagnosis, prognosis of treatment, and classification of periodontal disease." (PMID 35163727, 2022).
periodontal disease (continued). "A recent systematic review reported that the combination of MIP-1α, IL-1β, IL-6, and MMP-8 was acceptable as biomarkers for diagnosing periodontal disease." (PMID 34199256, 2021). "The reduced level of MMP-8 observed indicated clinical improvement of the periodontal disease as reflected by PPD, CAL, GI and BOP assessment." (PMID 33952216, 2021). "This is likely due to MMP-8 being an indicator of both, caries and active periodontal disease Furthermore, the heterogeneity of the patient cohort, were predominantly advanced disease stages and further studies are warranted to ascertain detection thresholds." (PMID 34575643, 2021). "As conclusions, MMP-8, TRAP-5, and OPG present a high precision potential in the identification of periodontal disease destruction, with MMP-8 as the most accurate diagnostic biomarker." (PMID 33143325, 2020). "Specifically, the presence of matrix metalloproteinase-8 (MMP-8, an enzyme responsible for tissue destruction) in GCF has been positively linked with periodontal disease progression." (PMID 32313785, 2020). "Biomarkers showing high levels in periodontal disease were salivary IL-1β, IL-4, IL-6, MMP-8, and tissue inhibitor of matrix metalloproteinases (TIMP)-2, and those in the controls were tumor necrosis factor (TNF)-α, IL-10, IL-17, and IL-32." (PMID 33383828, 2020). "MMP-8, TRAP-5, and OPG present a high precision diagnostic potential in the identification of periodontal disease destruction." (PMID 33143325, 2020). "The biomarkers showing elevated levels in the baseline saliva of patients with periodontal disease were IL-1β, IL-4, IL-6, MMP-8, and TIMP-2, while the control group showed high levels of TNF-a, IL-10, IL-17, and IL-32." (PMID 33383828, 2020). "MMP-8 is one of the major biomarkers of periodontal diseases and it has been found to be largely responsible for periodontal collagen degradation." (PMID 33263670, 2020). "As reported in a previous study, MMP-8, TRAP-5, and OPG in GCF showed a good discrimination performance at the site level to discriminate between healthy versus moderate to severe periodontal disease, especially MMP-8." (PMID 33143325, 2020). "MMP-8 is one of the most widely studied host-derived enzymes as a biomarker for periodontal disease, which is related to tissue destruction." (PMID 32503210, 2020). "Depending on the stage of periodontal disease progression, the biomarkers in saliva with high linkage are IL-1β in the immunologic phase and MMP-8 in the inflammatory phase." (PMID 33383828, 2020). "On the other hand, biomarkers of periodontal disease progression in GCF alone (MMP-8, MMP-9, Osteoprotegerin, C-reactive Protein and IL-1β) provided low sensitivity and high specificity values of 23% and 95%, respectively." (PMID 31817894, 2019). "Commercially available chair-side tests for MMP-8 to diagnose periodontal disease and PID activity are now available." (PMID 31817894, 2019). "MMP-8, MMP-9, and MMP-13 have been demonstrated to be associated with the severity of periodontal disease and are promising candidate biomarkers in oral fluids such as gingival crevicular fluid (GCF), mouthrinse, and saliva." (PMID 30669541, 2019). "It is believed that the MMP-8 level and the MMP-8/TIMP-1 ratio strongly correlate with clinical parameters in the periodontal disease such as the depth of gingival pockets or the bleeding in probing." (PMID 31781639, 2019). "Reviews on matrix metalloproteinases, especially MMP-8, in saliva and other oral cavity fluids for monitoring periodontal diseases have been recently published in Periodontology 2000 journal." (PMID 27143814, 2016). "In particular, it is established that the levels of MMP-8 in GCF correlate closely with the severity of periodontal disease and that levels decline in parallel to successful periodontal therapy." (PMID 24944840, 2014).